CYREN (cell cycle regulator of NHEJ)
Description:
Cell-cycle-specific regulator of classical non-homologous end joining (NHEJ) of DNA double-strand break (DSB) repair, which can act both as an activator or inhibitor of NHEJ, depending on the cell cycle phase. Acts as a regulator of DNA repair pathway choice by specifically inhibiting classical NHEJ during the S and G2 phases, thereby promoting error-free repair by homologous recombination during cell cycle phases when sister chromatids are present. Preferentially protects single-stranded overhangs at break sites by inhibiting classical NHEJ, thereby creating a local environment that favors homologous recombination. Acts via interaction with XRCC5/Ku80 and XRCC6/Ku70. In contrast, acts as an activator of NHEJ during G1 phase of the cell cycle: promotes classical NHEJ in G1 phase cells via multivalent interactions that increase the affinity of DNA damage response proteins for DSB-associated chromatin. Also involved in immunoglobulin V(D)J recombination (By similarity). May also act as an indirect regulator of proteasome (By similarity).
Synonyms: C7orf49; MRI; MGC5242; FLJ27285; CYREN-1; CYREN-2; FLJ22450; MRI-2
Tractability: No criterion of Open Targets' tractability assessment is met for any kind of drug.
Gene: Protein-coding gene on chromosome 7 (135,092,363 to 135,170,914, reverse strand). Ensembl gene ENSG00000122783.
Subcellular location: Cytoplasm (Isoform 1); Nucleus; Chromosome; Cytoplasm (Isoform 3); Cytoplasm (Isoform 4)
Gene Ontology:
Molecular function: protein binding; molecular adaptor activity; damaged DNA binding
Biological process: double-strand break repair via nonhomologous end joining; negative regulation of double-strand break repair via nonhomologous end joining; immunoglobulin V(D)J recombination; DNA damage response; positive regulation of double-strand break repair via nonhomologous end joining; protein localization to site of double-strand break
Cellular component: chromosome; cytoplasm; nucleus; site of double-strand break; DNA repair complex
Genetic constraint (gnomAD): Loss-of-function variants: 7 observed, 10.01 expected, observed/expected ratio (o/e) 0.7, 90% interval 0.4 to 1.31. The upper end of that interval is the gene's LOEUF score, 1.31, which puts it in group 5 of 6, group 1 being the genes least tolerant of losing a copy. Missense variants: 215 observed, 205.73 expected, observed/expected ratio (o/e) 1.05, 90% interval 0.93 to 1.17. Synonymous variants: 76 observed, 81.36 expected, observed/expected ratio (o/e) 0.93, 90% interval 0.77 to 1.13.
Homologues: Orthologues: chimpanzee CYREN (99% identical), macaque CYREN (93% identical), mouse Cyren (66% identical), rat Cyren (65% identical), guinea pig CYREN (59% identical), dog CYREN (56% identical).
Diseases named in the same sentence as CYREN in open-access papers:
CYREN is named in the same sentence as 3 diseases in open-access papers, as found by Europe PMC text mining. Sharing a sentence is not in itself a finding about the gene and the disease. The quoted sentences say what the papers report.
cancer (2 papers, 2021 to 2023). A tumor composed of atypical neoplastic, often pleomorphic cells that invade other tissues. "The same HERV3 locus has previously been described as a marker of response to immunotherapy in various cancers and lies downstream of the CYREN gene, of which an alternatively spliced transcript encodes the modulator of retrovirus infection (MRI-1) micropeptide." (PMID 34731091, 2021).
CYREN also shares sentences with these, for which no sentence is quoted: breast carcinoma (1 paper); ovarian carcinoma (1).